CCNK (cyclin K)
Diseases named in the same sentence as CCNK in open-access papers (continued):
Sharing a sentence is not in itself a finding about the gene and the disease.
pancreatic tumors (1 paper, 2018).
serous carcinoma (1 paper, 2025). "In serous carcinoma, CCNK expression exhibited significant heterogeneity." (PMID 40075638, 2025).
testicular tumors (1 paper, 2014). "Furthermore, cyclin K is highly expressed in human testicular tumors and seems to be required for tumor cell proliferation." (PMID 25004108, 2014).
triple-negative breast carcinoma (1 paper, 2024). An invasive breast carcinoma which is negative for expression of estrogen receptor (ER), progesterone receptor (PR), and human epidermal growth factor receptor 2 (HER2). "For this, we performed RNA sequencing (RNA-seq) in MDA-MB-231 cells, choosing triple-negative breast cancer cells as the relevant therapeutic context for CDK12/13–cyclin K inactivation." (PMID 37679459, 2024).
viral infection (1 paper, 2016). "In support of our notion, mass spectrometry analysis revealed that S130 in p21 is indeed phosphorylated in mitotic HeLa cells, although this residue is also phosphorylated by Cdk2/cyclin E in the S phase, Cdk6/cyclin K upon viral infection and ERK2 after mitogenic stimuli." (PMID 27384476, 2016).
cancer (23 papers, 2014 to 2026). A tumor composed of atypical neoplastic, often pleomorphic cells that invade other tissues. "The dysregulation of cyclin K (CCNK), a key regulator of transcription and cell cycle progression, has been implicated in cancer development." (PMID 40075638, 2025). "Their study also found that the increased expression of Cyclin K was associated with more advanced cancer stages." (PMID 37626854, 2023). "This review then provides a summary of current Cyclin K-associated cancer studies, with an emphasis on the available Cyclin K-targeting drugs." (PMID 37626854, 2023). "This process culminates in Cyclin K’s polyubiquitination and degradation, positioning HQ461 as a promising candidate for treating Cyclin K-associated cancers." (PMID 37669923, 2023). "First, understanding the genomic pattern and epigenomic control of Cyclin K will help us identify the mutation pattern of Cyclin K, the associated genetic alterations, and the underlying mechanisms for Cyclin K overexpression in cancers." (PMID 37626854, 2023). "Cyclin K is increasingly recognized as a key regulator in cancer biology, with studies linking its expression to tumor progression and cell proliferation, underscoring its potential as a therapeutic target." (PMID 40075638, 2025). "Cyclin K plays a pivotal role in cell division, DNA replication, and genomic stability, supporting cancer cell proliferation and therapy resistance." (PMID 40075638, 2025). "With frequencies ranging from 15% to 40%, cyclin K overexpression was seen in a variety of cancer types, which is consistent with its function in promoting tumorigenesis." (PMID 40075638, 2025). "Many authors emphasize that cyclin K actively participates in controlling cell proliferation and apoptosis, influencing the development and progression of malignant tumors." (PMID 40075638, 2025). "The ability to convert existing kinase inhibitors into degraders of key regulatory proteins like cyclin K opens new avenues for therapeutic intervention in cancers driven by dysregulated CDK12 activity." (PMID 39450271, 2024). "Depletion or loss of function of the CDK12/13/CCNK complex induces DNA damage through reduced expression of DDR genes and inhibits cell proliferation in cancer cells." (PMID 39353441, 2024). "In this study, we introduce YJ9069, a highly specific PROTAC degrader, targeting the CDK12/13/CCNK complex, demonstrating cytotoxicity at nanomolar concentrations across a spectrum of cancers." (PMID 39353441, 2024). "Together, these studies demonstrate that Cyclin K contributes to cell proliferation in cancer by regulating the following: the mitotic process, pre-RC assembly, and the protein abundance of β-catenin." (PMID 37626854, 2023). "The following examples are some of the interesting aspects for consideration in future Cyclin K-centered cancer studies." (PMID 37626854, 2023). "The specific purpose of this review is to delineate the role and therapeutic potential of Cyclin K in cancers." (PMID 37626854, 2023). "Although the deep-sequencing technologies employed granted easy access to the genomic and transcriptomic data, little is known about how Cyclin K is overexpressed in cancers." (PMID 37626854, 2023). "The involvement of Cyclin K in the DNA damage response pathway offers great opportunities in the context of radiotherapy and chemotherapy for cancer treatment." (PMID 37626854, 2023). "Third, investigating the function of Cyclin K in cancer development using genetically engineered mouse models is another way to increase our understanding of its role in cancer progression." (PMID 37626854, 2023). "The present research climate is promising for increasing our knowledge of Cyclin K to fight various cancers." (PMID 37626854, 2023). "Although the effect of PP-C8 on cancer cells was similar to Cyclin K or CDK12 depletion, the in vivo metabolic stability of this drug was not examined." (PMID 37626854, 2023).
cancer (continued). "Chemical-mediated Cyclin K degradation (e.g., dCeMM2/3/4, 7f, or 7b) has been shown to impair the viability of various cancer cells." (PMID 37626854, 2023). "In recent years, Cyclin K has been garnering increased research attention and is demonstrated as a critical player for cancer growth and therapeutic resistance." (PMID 37626854, 2023). "Current Cyclin K-related cancer studies focus on investigating the role of Cyclin K in tumor growth and therapeutic resistance." (PMID 37626854, 2023). "Given the importance of CDK9 and Cyclin K in DNA damage repair, studies in cancer models have focused on inhibiting CDK9 to generate increased replication stress and facilitate cancer cell death." (PMID 34207158, 2021). "Using RNA-Seq screening and pathway enrichment analysis, we found that Wnt/β-catenin signaling is the most significantly altered cancer-related pathway when Cyclin K was depleted." (PMID 33042275, 2020). "Therefore, the FLOS domain function via Cyclin K represents a unique therapeutic target for GC and other cancers." (PMID 40846851, 2025). "Finally, CR8 can be released rapidly by the cleavage of disulfide bonds under the high level of GSH in cancer cells to degrade cyclin K, which further induces the apoptosis of cancer cells." (PMID 39821590, 2025). "Finally, the current knowledge gaps regarding the potential of Cyclin K in cancers are discussed, along with interesting directions for future investigation." (PMID 37626854, 2023). "The combination of a Cyclin K degrader (e.g., dCeMM2/3/4, PP-C8, or 7f) and DNA-damage agents (e.g., cisplatin, irinotecan, olaparib, or MK-8776) produced synergistic effects in several different types of cancer cells." (PMID 37626854, 2023). "Therefore, it is possible that Cyclin K is a prime target for targeted therapeutics in treating cancer." (PMID 37626854, 2023). "It is, therefore, possible that the anti-cancer immunity is activated, or partially activated, by the degradation of Cyclin K. Whether and in what way Cyclin K contributes to immune suppression are valuable questions that merit further examination." (PMID 37626854, 2023). "They found that Cyclin K depletion dramatically reduced cancer cell proliferation." (PMID 37626854, 2023). "The biomedical significance of Cyclin K in cancers has been overlooked for some time." (PMID 37626854, 2023). "Studies have shown that Cyclin K regulates many essential biological processes, including the DNA damage response, mitosis, and pre-replicative complex assembly, and is critical in both cancer cell growth and therapeutic resistance." (PMID 37626854, 2023). "More work is needed to determine whether Cyclin K is indeed a master regulator for immune suppression in cancers." (PMID 37626854, 2023). "Importantly, the druggability of Cyclin K has been demonstrated in an increasing number of studies that identify novel opportunities for its use in cancer treatment." (PMID 37626854, 2023). "In addition, Cyclin K overexpression in cancers has been validated in cancer cell lines and cancer patient samples in the scientific literature." (PMID 37626854, 2023). "Given that for years, mitosis has been viewed as a promising cancer target, targeting Cyclin K or CDK12 may provide an alternative strategy for mitotic-based anti-cancer therapy." (PMID 37626854, 2023). "However, with an increasing number of studies demonstrating the promising druggability of Cyclin K in recent years, it is timely to redirect this focus toward understanding the involvement of Cyclin K in cancer biology." (PMID 37626854, 2023). "On the other hand, DDX27, RNF40, MMS22L and CCNK have not been reported as mutational cancer genes in previous studies." (PMID 34313788, 2021). "Additionally, DDX27, MDM2, RNF40, MMS22L, CCNK and LRP1B were detected as missense mutational cancer gene." (PMID 34313788, 2021).
cancer (continued). "To further explore whether Cyclin K directly controls cancer cell radiosensitivity, we performed clonogenic survival assays to ascertain cell survival after irradiation." (PMID 33042275, 2020). "In addition, it was reported that the Cyclin K/Cdk12 complex maintains genomic integrity and represents a master regulator of DNA damage response genes in various types of cancer 12-14." (PMID 33042275, 2020). "Collectively, we suggest that cyclin K may be a novel molecular link between germ cell development, cancer development and embryonic stem cell maintenance." (PMID 25004108, 2014). "Taken together, we suggest that cyclin K may be a novel molecular link between germ cell development, human cancer development and embryonic stem cell maintenance." (PMID 25004108, 2014). "Furthermore, the ectopic expression of Cyclin K in adult tissue resulted in cancer development." (PMID 37626854, 2023). "However, the functional role of Cyclin K in cancer is still poorly understood." (PMID 33042275, 2020). "In addition, cyclin K expression was easily detectable in various human cancer cell lines." (PMID 29760377, 2018). "For instance, in metastatic CRC, NCT02 acts as a molecular colloid that induces the ubiquitination and proteasomal degradation of cyclin K (CCNK) and its partner CDK12, leading to apoptosis of cancer cells." (PMID 38485957, 2024). "SR4835 was used in mouse models in several studies to investigate the role of Cyclin K, CDK12, or CDK13 in cancers." (PMID 37626854, 2023). "The expression levels of CDK12 and its partner cyclin, cyclin K (CCNK), are unchanged throughout the normal cell cycle but are frequently elevated in proliferating stem cells and cancer cells." (PMID 32451425, 2020). "It will be interesting to test whether HQ461, by depleting CCNK, also enhances the therapeutic efficacy of PARP inhibitors for cancer treatment." (PMID 32804079, 2020). "Inhibition of CDKs by small-molecule compounds has already been achieved in many studies, and these inhibitors will be great opportunities for cancer therapy, but the specificity against CDK/cyclin K complexes and the locus dependency on chromatin remain unclear." (PMID 36450243, 2022). "We considered the possibility that cyclin K protein level might be so high in those cancer cells that it could not be further increased by external signals." (PMID 29760377, 2018). "First, a striking functional dependency on both CCNK and CDK12 is evident across most cancer cell lines, as demonstrated by pan-cancer negative CRISPR scores." (PMID 41491919, 2026).
tumor (11 papers, 2015 to 2026). "Next, we performed multiple pathway analysis and found that the Wnt signaling pathway, which is closely associated with tumor progression and radioresistance, was markedly enriched, indicating that cyclin K may represent a critical regulator of Wnt signaling." (PMID 33042275, 2020). "In addition to regulating gene transcription, Cyclin K has also been implicated in the control of cell proliferation and apoptosis, indicating that Cyclin K may play indispensable roles in tumor development and progression." (PMID 33042275, 2020). "The initial phase focused on the immunohistochemical evaluation of CCNK expression and distribution in EC tissues and adjacent non-tumor tissues." (PMID 40075638, 2025). "These similar immunohistochemical results in the two tumors highlight how CCNK promotes tumor growth in an oncogenic manner." (PMID 40075638, 2025). "On the other hand, CCNK mRNA expression was considerably higher in tumor tissues in nEAC than in nearby normal tissues (p = 0.0445)." (PMID 40075638, 2025). "These analyses aimed to elucidate the transcriptional landscape of CCNK and its potential regulatory networks in tumor biology." (PMID 40075638, 2025). "One large cohort’s immunohistochemical analyses showed a strong correlation between advanced tumor stages and poor OS and high cyclin K expression." (PMID 40075638, 2025). "Of 133 samples with RNA-seq data available, CUL4A and CCNK expression of the tumor was significantly higher than that in normal tissue." (PMID 36272974, 2022). "There was also a significant correlation between Cyclin K expression and tumor stage in clinicopathological parameters (p < 0.05)." (PMID 33042275, 2020). "Our results broaden our knowledge by suggesting that transcriptional control and cellular homeostasis mechanisms may also be involved in tumor aggressiveness due to elevated CCNK expression in nEAC." (PMID 40075638, 2025). "Combining cyclin K/CDK12/CDK13 degrader, NCT02, with oxaliplatin and irinotecan exhibited synergistic anti-tumor effects in metastatic CRC cells." (PMID 41491919, 2026). "High CCNK expression is associated with poorer survival in all patients with EC and is particularly relevant in the non-endometrioid subtype, where it may contribute to tumor aggressiveness." (PMID 40075638, 2025). "This notion predicts that tumor cells overexpressing cyclin E1 should need high level of CDK12 and/or cyclin K to sustain high rate of proliferation." (PMID 29760377, 2018). "This demonstrates how cyclin K is significantly overexpressed in tumor tissues as opposed to nearby non-tumorous tissues." (PMID 40075638, 2025). "There were no discernible variations in CCNK mRNA expression between tumor tissues and nearby normal tissues in the entire EC cohort (p = 0.3114) or the eEAC subtype (p = 0.8112), suggesting that these groups exhibited consistent expression patterns." (PMID 40075638, 2025).
neurodevelopmental disorder (3 papers, 2019 to 2021). A behavioral and cognitive disorder with onset during the developmental period that involves impaired or aberrant development of intellectual, motor, or social functions. "Moreover, four unrelated Chinese children affected by neurodevelopmental disorder with facial dysmorphism have been reported to harbor potentially pathogenic CCNK gene (gene responsible for coding of cyclin K) mutations with de novo inheritance." (PMID 33805800, 2021). "Importantly, heterozygous copy number loss of CCNK gene in humans caused a syndromic neurodevelopmental disorder with distinctive facial dysmorphism." (PMID 31440507, 2019). "Recently, a new syndromic neurodevelopmental disorder with facial dysmorphism was described in four unrelated individuals, who harbor de novo heterozygous changes affecting CCNK (cyclin K coding gene)." (PMID 32762766, 2020).
adenocarcinoma (1 paper, 2025). A common cancer characterized by the presence of malignant glandular cells. "Elevated levels of CDK12 and CDK13, which form complexes with CCNK, were also associated with worse OS outcomes in patients with adenocarcinoma." (PMID 40075638, 2025).
CCNK also shares sentences with these, for which no sentence is quoted: adenosis (1 paper); ataxia telangiectasia (1); breast tumor (1); cholangiocarcinoma (1); esophageal carcinoma (1); Fanconi anemia (1); Fibroadenoma (1); glioma (1); infection (1); lobular breast carcinomas (1); melanoma (1); microcephaly (1); myeloma (1); pancreatic adenocarcinoma (1); Spastic paraplegia 7 (1); stomach adenocarcinoma (1); thymoma (1).